APC (APC regulator of Wnt signaling pathway)
Diseases named in the same sentence as APC in open-access papers (continued):
Sharing a sentence is not in itself a finding about the gene and the disease.
tumor (continued). "Conversely 7(16%) other tumor tissues were methylated for both alleles of APC, indicating that their corresponding tissues were homogeneous and composed of only one type of cells." (PMID 19149902, 2009). "APC is also commonly mutated in many tumour types including colon and gastric, with the majority of mutations occurring in the mutation cluster region." (PMID 19293793, 2009). "APC methylation was associated with histological grade and tumour stage but this should be confirmed on a larger data set." (PMID 18841156, 2008). "This study was conducted to detect the mutations in APC gene in blood and tumor samples collected from 16 patients (10 men and 6 women) and blood samples from 21 first and second degree relatives of the patients." (PMID 20108522, 2008). "We initiate this study to detect the mutations in APC gene in blood and tumor samples collected from 16 patients (10 men and 6 women) and blood samples from 21 first and second degree relatives of the patients." (PMID 20108522, 2008). "Strikingly, this experiment unequivocally demonstrated that from the 16 tumor suppressor genes that were scrutinized DNMT3b down-regulation caused specific loss of methylation at the promoters of APC, RAR-β, and Rb1 genes (Figure-3)." (PMID 18798999, 2008). "Since APC inactivation is sufficient to initiate tumour development, APC mutation affect degradation of α-catenin and truncated APC fragments stimulate colorectal cancer cell migration and generate chromosomal instability." (PMID 20108522, 2008). "As predicted by the 'just right' model for the APC tumor suppressor gene, the molecular nature of the first hit at a tumor suppressor locus affects the type of second-hit mutation at the wild-type allele." (PMID 19014666, 2008). "We have also demonstrated that the APC gene mutation is a relatively common and early event in I-phenotype tumours, but rather rare in G-phenotype tumours, especially tumours showing HGM expression." (PMID 17262083, 2007). "Primary cell cultures from an aggressive fibromatosis tumor harbouring a truncating APC mutation were established." (PMID 17407603, 2007). "In mitosis, APC localises to kinetochores in a microtubule dependent manner, and tumour cells with APC mutations have weaker kinetochore – microtubule interactions." (PMID 17697341, 2007). "In mice, APC mutation enhances genomic instability and tumour formation in cells haploinsufficient for BubR1, a spindle checkpoint kinase." (PMID 17697341, 2007). "Overexpression of the transcriptional activator β-catenin, mostly owing to loss-of-function mutations of the adenomatous polyposis coli (APC) tumour suppressor gene, is crucial for the initiation and progression of human colorectal carcinogenesis." (PMID 16705313, 2006). "Although in our study the simultaneous occurrence of hMLH1 deficiency as well as an APC or K-ras mutation was observed in a small number of tumours, the mutually exclusive occurrence of hMLH1 deficiency and mutations in APC and/or K-ras seemed to predominate." (PMID 16356174, 2005). "Tumours with truncating APC mutations and activating K-ras mutations in codons 12 and 13 occurred at similar frequencies (37% (245/656) and 36% (235/656), respectively)." (PMID 16356174, 2005). "FAP, an inherited tumour predisposition, is caused by mutant alleles of the adenomatous polyposis coli (APC) gene and provides an opportunity to define critical early genetic events in the development of tumours." (PMID 15982419, 2005). "Although APC and K-ras mutations are often observed seperately in a tumour, these mutations seem to also occur in a co-dependent manner." (PMID 16356174, 2005).
tumor (continued). "Although tumours harbouring both mutations were relatively rare, mutations in APC and K-ras seemed to occur co-dependently." (PMID 16356174, 2005). "Activated Wnt signalling in tumours is caused by increased levels of β-catenin, which can be the result of mutations in APC, β-catenin, AXIN1, AXIN2 or β-TrCP." (PMID 14970870, 2004). "Although recent investigations have been focused on the role of the adenomatous polyposis coli (APC)/ β-catenin/Tcf pathway in human tumorigenesis, there have been very few reports on mutations of the β-catenin gene in a variety of tumour types." (PMID 11437403, 2001). "Notably, valproic acid also promotes the degradation of HDAC2 and has been shown to reduce the proliferative advantage of APC‐mutated cells, thereby inhibiting tumor progression." (PMID 40060193, 2025). "Specifically, APC mutations were significantly more prevalent in H/L patients (3.6% vs. 0.8%, p = 0.05), which may have implications for disease progression and tumor behavior." (PMID 40227587, 2025). "The major changes in tumor biology observed with correction of the BRAFV600E mutation are reminiscent of the reversal of CRC cells to normal cells following re-expression of wildtype APC." (PMID 40687798, 2025). "The APC gene is a tumor suppressor gene that encodes a multidomain protein." (PMID 40429703, 2025). "The observed trend toward reduced PFS in APC-mutated tumors aligns with prior studies suggesting that APC truncating mutations may promote tumor aggressiveness through dysregulation of Wnt/β-catenin signaling, a pathway central to colorectal carcinogenesis." (PMID 40687430, 2025). "For instance, mutation of the APC gene has been shown to enable the transcription of genes involved in protein synthesis and the cellular stress response, leading to translation deregulation and tumor growth." (PMID 40141206, 2025). "APC is a classic tumor suppressor gene, requiring both alleles to be mutated for loss of function." (PMID 41091816, 2025). "This suggests that the inflammatory environment following DSS administration might promote APC allele loss, resulting in increased genetic instability and enhanced tumor formation." (PMID 41285904, 2025). "Likewise, miR-31, together with miR-18a and miR-21-5p, was identified among the most upregulated miRNAs associated with APC gene alterations by another differential expression study conducted on 40 CRC tumor samples and in their paired normal counterpart." (PMID 40535722, 2025). "In GC, overexpression of Wnt ligands (Wnt2, Wnt3, and Wnt5A) and receptors (FZD7 and LRP5/6) is associated with more advanced disease, poorer prognosis, and elevated metastatic potential, while β-catenin and reduced APC expression further underline more aggressive tumor behavior." (PMID 40943055, 2025).
tumor (continued). "A recent study suggests that cooperation between founder clones with different APC mutations can achieve “just-right” conditions for tumor development; hence, disagreement with the “just-right” model might be due to the polyclonality of some polyps in FAP." (PMID 41091816, 2025). "Mutations in APC are strongly associated with tumor initiation and progression in CRC." (PMID 40722723, 2025). "Analysis of tumor development and progression demonstrated that mice with both the APC mutation and p16 epigenetic alteration exhibited significantly reduced survival times and enhanced tumor growth compared with mice harboring the APC mutation alone." (PMID 39836268, 2025). "Indeed, APC mutations correlate with a low presence of immune checkpoint targets and low tumor mutational burden (TMB)." (PMID 38791382, 2024). "Over-expression of both PD-L1 (on different tumor cell types and tumor-associated APC) and PD-L2 (primarily on hematologic cancer cells and tumor-associated APC) is also caused by inflammatory stimuli and signaling networks that are frequently active in tumor micro-environments." (PMID 39127974, 2024). "This has important clinical implication as the APC: c.835-8 A > G somatic mutation may represent a biomarker for colibactin-induced DNA damage in CRC tumours caused by pks+E." (PMID 38200234, 2024). "Furthermore, the specific genomic alterations, such as CDKN2A and APC mutations, associated with the formation of C0 and C1 subpopulations provide insight into the potential drivers of tumour cell heterogeneity." (PMID 38279519, 2024). "Targeted cancer gene panel sequencing of the primary tumor specimens identified a few additional mutations, including one patient each with pathogenic germline mutations in APC and ARID1A, while the remaining mutations were variants of unknown significance." (PMID 39567523, 2024). "Biased competition that favours fixation of loss-of-function of the tumour suppressor APC has recently been ascribed to ‘supercompetitor’ behaviour, comprising both cell-intrinsic behaviours and non-cell autonomous suppressive effects on wild-type ISC neighbours." (PMID 39478206, 2024). "Interestingly, genetic analyses showed that when EphB6 overexpression is accompanied by mutations in the APC gene, the tumor gains significant advantages in cell proliferation, invasion, and metastasis." (PMID 38651144, 2024). "The loss of expression of APC in the intestinal epithelium results in tumor formation." (PMID 39056778, 2024). "Prior research has indicated that CDC27 may function as either a tumor suppressor or an oncogene in various neoplasms, and the activation of APC/C is thought to be linked to their pathogenesis." (PMID 38731925, 2024). "This leads to the assumption that APC mutations are dispensable for tumor initiation." (PMID 39390564, 2024). "Chromosome microarray was undertaken on this tumor, which identified biallelic APC gene loss." (PMID 39597961, 2024). "The APC gene is a tumour suppressor that is frequently mutated in familial cases of CRC." (PMID 39456841, 2024). "We investigated whether partial loss of discreet domains within APC allow de novo protein-protein interactions, towards which tumours could become addicted." (PMID 39443725, 2024). "However, in this study, we only observed possible truncating driver mutations in RNF43 and APC among plasma samples at very low (<2%) allele frequency and these mutations were different than those observed in matched tumor samples." (PMID 36454217, 2023).
tumor (continued). "Although neoplasia associated with APC mutation is generally ascribed to the activation of canonical Wnt/β-catenin target genes, APC suppresses other downstream targets, and these are also activated by an APC loss of function mutations." (PMID 37489330, 2023). "Furthermore, mutations in the APC2 gene, which are directly linked to APC’s tumor-suppressive function, are also associated with worse prognosis in CRC patients." (PMID 37835512, 2023). "Similarly, APC2 mutations, which are directly associated with APC’s tumor-suppressive function, have been linked to worse prognosis in CRC patients." (PMID 37835512, 2023). "Indeed, a confounding factor is the enrichment of BRAF mutations in the APC wild-type tumours (p = 1.4 × 10−10, Fisher’s exact test)." (PMID 37666855, 2023). "Epithelial barrier damage may be a consequence of β-catenin activation as well as loss of APC, microbial products drive IL-23/IL-17-mediated tumor growth." (PMID 38156313, 2023). "The presence of APC mutation has been found to be correlated with a decreased tumor mutation burden (TMB), increased tumor purity (TP), reduced expression of immune checkpoint molecules (PD-a, PD-L1, PD-L2), decreased microsatellite instability, and an up-regulated mismatch repair pathway." (PMID 37763765, 2023). "Our findings provide direct evidence that USP7 inhibition may offer a safe and efficacious tumor-specific therapy for both sporadic and germline APC-mutated CRC." (PMID 36669491, 2023). "The marked differences in APC mutational frequency among populations may reflect on the molecular pathways that lead to tumor progression, suggesting that for PRH, the most common one is the CIN pathway." (PMID 37039257, 2023). "Hence, the abnormal expression of UBE2C will cause the hyperactivity of the APC/C-dependent ubiquitination in tumor cells, which accelerates the cell cycle and eventually leads to malignant transformation." (PMID 37535572, 2023). "The protein level of APC was negatively associated with nuclear localization of β-catenin and Oct4 expression, and nuclear β-catenin was positively correlated with Oct4 expression in tumor tissues." (PMID 37746658, 2023). "Additionally, patients who inherit germline mutations in APC are susceptible to spontaneous tumor development, mostly in the colon, but also throughout the gastrointestinal tract including in the duodenum and stomach with variable penetrance." (PMID 35658010, 2022). "For now, care must be taken before designating Tregs to be responsible for IL-33-mediated CRC (in particular APC-mutation-mediated CRC) in settings where there is a concomitant rise in tumour Treg infiltration and increased cancer burden, in the absence of functional assessments." (PMID 36263033, 2022). "Whether it is the acquisition of DCLK1+ expression by tumour stem cells due to aberrant Wnt signaling (for example due to loss of APC) which leads to their ability to produce IL-25 remains to be explored." (PMID 36263033, 2022). "Additionally, the ssGSEA algorithm suggested that tumor-infiltrating cells, Tregs, checkpoint, inflammation-promoting, APC, HLA, and IFN responses were highly active in the high-risk group." (PMID 36618700, 2022).
tumor (continued). "In tumor number 1061, a large deletion was found in one allele of APC, resulting in loss of heterozygosity, whereas the other allele had a disruptive frameshift deletion that probably eliminated APC function." (PMID 35343095, 2022). "Both APC mutations in this tumor had allele variant fractions of 40–50%." (PMID 36181537, 2022). "In addition, APC-deficient ISC clones further increase their fitness through the modulation of the tumor microenvironment by secreting Wnt antagonists such as Notum." (PMID 35053565, 2022). "APC gene mutations cause tumor in patients with FAP and 15% sporadic tumors." (PMID 35478728, 2022). "Furthermore, the oncogenic functions of Mex3a were further validated when Mex3a was deleted in Vil-Cre;APCfl/+mice, in which APC mutation-driven tumor mouse model is relevant to human familial CRC." (PMID 36276637, 2022). "This suggests that, although the IS2 tumor may derive primarily from APC mutation, the pathogenesis of tumors in this subtype may be much more complex than the other ISs." (PMID 35967414, 2022). "Apart from the conventional pathway that is typically initiated by characteristic APC mutation and chromosomal instability, the serrated neoplasia pathway is mainly characterized by mutations of BRAF or KRAS, microsatellite instability (MSI), and CpG island methylator phenotype (CIMP)." (PMID 33382354, 2021). "The co-occurrence of mutations may be associated with their presence in specific tumor types, i.e., the APC and KRAS alterations (p < 0.01) in CRC." (PMID 33742104, 2021). "JW55 also reduces the growth of tumor in conditional APC mutation mice." (PMID 34381360, 2021). "Mutation of APC is another important driver for tumor formation." (PMID 34488905, 2021). "Furthermore, APC mutations have been shown to induce chemoresistance through angiogenesis by interacting with the tumour microenvironment." (PMID 34934968, 2021). "In addition, the critical role of PKM2 in tumour growth induced by APC-mutated CRC cells was confirmed in vivo by xenograft mouse model." (PMID 33071283, 2021). "When they specifically targeted Lgr5−/Krt19+ cells with an inducible APC homozygous mutation, these cells initiated autochthonous malignant tumors containing mutated Lgr5+ cells—therefore generated through cell dedifferentiation—that drove tumor development." (PMID 33671641, 2021). "Notably, tumorigenesis selects for APC mutants with a residual ability to downregulate β-catenin and, furthermore, the spectrum of APC mutations in tumours varies along the length of the intestine, reflecting local variations in Wnt-signal strength." (PMID 33673710, 2021).